MTOR (mechanistic target of rapamycin kinase)
Diseases named in the same sentence as MTOR in open-access papers (continued):
Sharing a sentence is not in itself a finding about the gene and the disease.
COVID-19 (continued). "Targeting Akt-mTOR signaling could be an attractive candidate for a potential therapy, alone or preferably combined with antivirals, for the management of COVID-19 patients and needs further evaluation." (PMID 32691695, 2020). "We hypothesized that the reported activation of the mTOR pathway and the upregulated production of pro-inflammatory cytokines in COVID-19 will represent novel valuable theranostics for the prevention and treatment of Neuro-COVID." (PMID 33198412, 2020). "Furthermore, mTOR signaling in pDCs was reduced significantly in COVID-19–infected individuals, as measured by decreased pS6 signaling by mass cytometry." (PMID 32788292, 2020). "Recently, mTOR inhibition therapy has been hypothesized to mitigate the cytokine storm and to reduce hyperactivation of immune responses in COVID-19." (PMID 33414726, 2020). "Since mTOR inhibitors can cause interstitial pneumonitis and lead to ground glass opacity abnormality in chest CT scan, switching mTOR inhibitor to CNI should be considered among COVID-19 SOT patients with typical ground opacity chest CT scan." (PMID 32612614, 2020). "mTOR-dependent pathways may uncover molecular targets useful for controlling the cellular damage, oxidative stress, and hyperinflammation that occur in COVID-19." (PMID 33414726, 2020). "mTOR blockade by rapamycin may inhibit Th17 cell expansion in COVID-19 patients similarly to SLE patients." (PMID 33361522, 2020). "Consequently, future clinical research should investigate these therapeutic effects in greater depth, with particular emphasis on elucidating the involvement of the mTOR signaling pathway to better define its specific role and mechanism in the treatment of COVID-19." (PMID 41282609, 2025). "Thus,mTOR inhibitors may provide a survival benefit in kidney transplant patients with COVID-19, highlighting the need for furtherresearch." (PMID 40978637, 2025). "Together these findings suggest that MTOR signaling and its impact on ROS and metabolism play an important role in the pathophysiology of COVID-19, and drugs targeting several of these pathways could have synergistic effects with consequences on disease progression and severity." (PMID 38981682, 2024). "In summary, PTEN and mTOR may be potential targets of metformin for the treatment of COVID-19/LUAD." (PMID 38811809, 2024). "In addition, binding of SARS-CoV-2 to ACE2 in enterocytes possibly results in reduced activation of canonical autophagy regulator mTOR, thereby enhancing intestinal autophagy and promoting the development of extrapulmonary COVID-19 clinical manifestations such as diarrhoea." (PMID 36951188, 2023). "Predisposition to severe symptoms and negative prognosis of COVID-19 has shown to be related with production of cytokines and pro-inflammatory molecules, dysregulation of mammalian target of rapamycin (mTOR), and alteration in the number of innate cells, their activation and polarization." (PMID 37292210, 2023). "Of the 11 patients infected, 7 (63.6%) had COVID-19; in particular, six had a mild form of the disease, while 1 had a moderate form of the disease (OR for moderate/severe form vs. mild:0.8, 95, CI: (0.21–0.92) mTOR inhibitors recipients vs. other regimens; p = 0.041)." (PMID 35801204, 2022). "Meanwhile, QFPD may play a role in COVID-19 treatment by targeting mTOR and PLA2G4A." (PMID 36210820, 2022). "Finally, our findings reveal that SARS-CoV-2 infection in Vero E6 cells and severe COVID-19 patients occur in conditions of increased mTOR activity and impaired autophagic flux that could influence viral replication." (PMID 36661509, 2022). "Therefore, it is unquestionable that mTOR-Is could act as a double edge sword in patients with COVID-19 and a correct use of this medication may have a “yin or yang” clinical effects." (PMID 34497515, 2021).
COVID-19 (continued). "Therefore, for kidney transplant recipients suffering from symptomatic COVID-19, clinicians should first choose to reduce or stop ADs or mTOR inhibitors instead of CNIs, and when the illness progresses to severely symptomatic COVID-19 at that time, the withdrawal of CNIs will be considered." (PMID 34681278, 2021). "Therefore, it is reasonable to hypothesize that the induction of mTOR, the central regulator of autophagy, might be an effective therapeutic avenue against COVID-19-mediated diarrhea, and its complications." (PMID 34206057, 2021). "Therefore, everolimus mediated inhibition of mTOR activity may exert differential outcomes in COVID-19 patients by mitigating the cytokine storm and hyper-reactivity in the critical phase of the disease." (PMID 34054782, 2021). "Other Food and Drug Administration-approved antiinflammatory drugs tested in models of SEB TSS may also be effective, including CTLA4-Ig which can inhibit CD28 costimulation, and the mammalian target of rapamycin (mTOR) inhibitor rapamycin, which is already in use for COVID-19." (PMID 32989130, 2020). "Whether the currently proposed drugs targeting the Akt/mTOR pathway can be indeed repurposed for COVID-19 therapies now needs to be tested carefully in in vitro SARS-CoV-2 infection models and in in vivo COVID-19 disease models as improper regulation may pose a detrimental effect." (PMID 32691695, 2020). "In an Italian series of cancer patients infected with COVID-19 in a 1-month duration, BC patients represented five of 17 patients, of whom two were on chemotherapy, one was on adjuvant endocrine therapy and two patients were on mTOR inhibitors or an anti-Her2 agent in the metastatic setting." (PMID 32715776, 2020). "Post COVID-19 residual findings at CT-scan before (T0) and after (T6) 6 months follow up of immunosuppressive therapy with MMF/MYF or mTOR-i in kidney transplant recipients enrolled in the study." (PMID 40568197, 2025). "Patients with COVID-19 exhibit stronger humoral immunity, elevated Rho-GAP and mTOR pathway activities, and higher IFN-I signaling." (PMID 40076669, 2025). "This study systematically elucidates the molecular mechanisms by which traditional Chinese medicine treats COVID-19 by regulating key signaling pathways such as PI3K/Akt, NF-κB, JAK/STAT, and mTOR." (PMID 41282609, 2025). "We first studied mTOR signaling in scRNA-seq datasets of whole blood and PBMC samples of COVID-19 cohorts." (PMID 40177636, 2025). "They identified 40 intersection targets between cepharanthine and COVID-19, with key targets primarily involving Src, AKT1, EGFR, and mTOR, among others." (PMID 41303371, 2025). "Inspired by this network analysis, we queried the STRING database by including p70S6K (gene name RPS6KB1) and mTOR as representative proteins for the PI3K/mTOR pathway, along with a list of closely related COVID-19 proteins based on the DISEASES database." (PMID 39513867, 2024). "Many of the pathways that SiPSiC found to be upregulated in the alveolar cells of the COVID-19 group were of therapeutic potential, including DNA repair, UPR, PI3K/AKT/MTOR signaling, ROS, and metabolic pathways." (PMID 38981682, 2024). "We identified PTEN, mTOR, and PPARA as possible core target genes for metformin in the treatment of COVID-19/LUAD by screening genes based on their expression levels." (PMID 38811809, 2024). "On the other hand, eight out of ten anti-COVID-19 core targets (TNF, EGFR, CASP3, AKT1, MAPK1, MAPK3, mTOR, and IL-6) followed the human cytomegalovirus infection." (PMID 36817449, 2023). "Nine of ten anti-COVID-19 core targets (HIF1A, EGFR, CASP3, AKT1, MAPK1, MAPK3, HSP90AA1, mTOR, and IL-6) followed the pathways in cancer." (PMID 36817449, 2023). "We found that T cells in patients with COVID-19 showed increased mTOR pathway activity, while T cells in HIV-1+ patients showed downregulated mTOR activity, compared to healthy controls, (top)." (PMID 36992700, 2023).
COVID-19 (continued). "The top 10 of 41 potential anti-COVID-19 core targets (AKT1, TNF, HSP90AA1, IL-6, mTOR, EGFR, CASP3, HIF1A, MAPK3, and MAPK1) were identified as molecular targets of key active phytonutrients of the Meliae cortex that might be implicated in ameliorating COVID-19." (PMID 36817449, 2023). "Since the mammalian target of rapamycin (mTOR) is modulated in SARS-CoV-2 infected cells, rapamycin, an mTOR inhibitor, can be repurposed at low dosages for the treatment of COVID-19." (PMID 36982738, 2023). "The top three Meliae cortex’s key active phytonutrients were further analyzed for molecular docking with the top ten anti-COVID-19 core targets, including AKT1, TNF, HSP90AA1, IL-6, mTOR, EGFR, CASP3, HIF1A, MAPK3, and MAPK1." (PMID 36817449, 2023). "The top ten anti-COVID-19 core targets, AKT1, TNF, HSP90AA1, IL-6, mTOR, EGFR, CASP3, HIF1A, MAPK3, and MAPK1, were chosen for molecular docking studies with the Meliae cortex’s key active phytonutrients determined in section 3.7." (PMID 36817449, 2023). "This further stimulates several intracellular cytokines, such as NF-κB, mTOR, TNF- α, etc., that contribute to COVID-19’s pathophysiology." (PMID 36817449, 2023). "Hence, Akt/mTOR inhibitors could prove a valuable asset in COVID-19 management." (PMID 36389723, 2022). "In the context of infectious diseases (e.g., COVID-19, influenza, pneumonia), there might also be opportunities to improve the immunological status while acting on the background biology of aging through pharmacological interventions (e.g., low-dose mammalian Target of Rapamycin [mTOR] inhibitors)." (PMID 36346720, 2022). "TNF, GAPDH, MAPK3, MAPK1, EGFR, CASP3, MAPK8, mTOR, IL-2, and MAPK14 are important targets for YQS in COVID-19 treatment." (PMID 35340244, 2022). "We also built a cross-network that included the cellular senescence pathway, the mTOR pathway, the MAPK signaling pathway and the Coronavirus disease-COVID-19." (PMID 36685935, 2022). "Examination of informative model features reveals biological signatures of COVID-19 severity, including the dysregulation of JAK/STAT, MAPK/mTOR, and nuclear factor κB (NF-κB) immune signaling networks in addition to recapitulating known hallmarks of COVID-19." (PMID 35839768, 2022). "Furthermore, mTOR pathways in conjunction with AMPK may be therapeutic targets for controlling cell injury, oxidative stress, mitochondrial dysfunction, and the onset of hyperinflammation, a significant disability associated with COVID-19." (PMID 35078427, 2022). "Considering the need for drugs to treat COVID-19, the α-hydroxylinoleic acid (ABTL0812) induces the expression of TRIB3 by inhibiting the PI3K/AKT/mTOR axis and promoting autophagy cell death in cancer." (PMID 33532126, 2021). "Second, metformin inhibits the mTOR signaling pathway, thus reducing SARS-CoV-2 infectivity and COVID-19 mortality." (PMID 34348687, 2021). "The absence of COVID-19-related deaths in patients on mTOR CNI-free regimens suggests potential protective effects that merit further investigation." (PMID 41600794, 2025). "The results of bioinformatics analysis showed that the mechanism of metformin in COVID-19/LUAD might be related to energy metabolism, NADH oxidoreductase activity, FoxO signalling pathway, AMPK signalling pathway, and mTOR signalling pathway." (PMID 38811809, 2024). "Furthermore, Cytoscape software was used to visualize the degree of each gene in the PPI network, and PTEN, mTOR, and PPARA were identified as core targets for metformin treatment against COVID-19/LUAD due to their high degree within the network." (PMID 38811809, 2024). "In addition, cluster 1 confirms the existence of the top ten potential anti-COVID-19 core targets (AKT1, TNF, HSP90AA1, IL-6, mTOR, EGFR, CASP3, HIF1A, MAPK3, and MAPK1); consequently, the results of the PPI and cluster network analyses are congruent." (PMID 36817449, 2023).
COVID-19 (continued). "mTOR is a target in IPF, and two recent studies showed that mTOR might be an anti-SARS-CoV-2 target, with rapamycin being considered in COVID-19 patients." (PMID 37371834, 2023). "It has also been reported that SRCs contribute to HIV reactivation via mTOR and STAT2, and MACROH2A1-SRC family axis may regulate the inflammatory pathogenesis of COVID-19." (PMID 36451245, 2022). "Though we found activation of the mTOR signaling in SARS-CoV-2 infected cells, our single-cell analysis of severe COVID-19 patients revealed that mTOR signaling is not altered between infected and bystander cells." (PMID 36661509, 2022). "We found that both infected and bystander (not infected) BALF epithelial cells of severe COVID-19 patients presented upregulation of mTOR signaling genes, including SQSTM1 and CDKN1A." (PMID 36661509, 2022). "Moreover, p38 mitogen activated protein kinase (p38MAPK), mechanistic target of rapamycin (mTOR) and high mobility group box protein 1 (HMGP1) are also activated in COVID-19, leading to the release of pro-inflammatory cytokines." (PMID 35783600, 2022). "The patients of COVID-19, MM, and DLBCL may also be treated with specific inhibitors of the PI3K/Akt/mTOR pathway." (PMID 36466549, 2022). "Hence, mTOR inhibitors, synthetic and mainly naturally available compounds, should be screened to determine their potency to suppress SARS-CoV-2 infection and COVID-19." (PMID 34179893, 2021). "Only a few episodes of acute rejections have been related to a decrease in immunosuppression, suggesting that in the case of COVID-19-related lymphopenia, the temporary cessation of CNI, MPA, or mTOR inhibitors may be safe even for 2 weeks." (PMID 34578460, 2021). "Here, we briefly discuss natural compounds that affect endolysosomes and autophagy, the mTOR sensor, and as such, might find therapeutic use against SARS-CoV-2 infection and the pathogenesis of COVID-19." (PMID 33768214, 2021). "Such a severe COVID-19 outcome did not occur with mTOR inhibitors or CNI, and complete immunosuppression withdrawal showed no benefit." (PMID 34578460, 2021). "Here briefly concludes that the mTOR sensor might be a potential therapeutic target to suppress SARS-CoV-2 infection and its pathogenesis, COVID-19." (PMID 34179893, 2021). "Immunosuppressants such as calcinurine inhibitors (CNIs) and the mechanistic target of rapamycin (mTOR) inhibitors have shown inhibitory effects on the replication of MERS-CoV and SARS-CoV in vitro and thus might also be beneficial in COVID-19." (PMID 34692845, 2021). "Accordingly, the greater endolysosome pathway including autophagosomes and the mTOR sensor may be targets for therapeutic interventions against SARS-CoV-2 infection and COVID-19 pathogenesis." (PMID 33768214, 2021). "Rapamycin, an mTOR inhibitor with the capacity to promote autophagy and suppress SASP, may restore T-cell functionality and attenuate cytokine storm in COVID-19." (PMID 33361522, 2020). "The data therefore points towards dysregulation of Akt/mTOR/HIF-1 signaling cascades, which could be a potential target for COVID-19 therapeutic interventions." (PMID 32691695, 2020). "Known data shows mTOR inhibitors may reduce mortality in kidney transplant patients with COVID-19 compared to other immune-suppressants.However, they do not significantly impact disease severity." (PMID 40978637, 2025). "However, there is no clinical evidence that CNI and mTOR inhibitors, with or without reduction of dosage, improve COVID-19-related outcomes in KTRs." (PMID 38313994, 2024). "Of note, the higher BMI in the group not taking mTOR inhibitors regularly may have led to more severe COVID-19 symptoms." (PMID 38956624, 2024). "This underscores that mTOR inhibitors do not aggravate the symptoms of COVID-19 in LAM patients." (PMID 38956624, 2024).
COVID-19 (continued). "Metformin may be able to cure COVID-19/LUAD comorbidity through energy metabolism, oxidoreductase NADH activity, FoxO signalling pathway, AMPK signalling system, and mTOR signalling pathway, among other pathways, according to the results of bioinformatic research." (PMID 38811809, 2024). "COVID-19 pathology may be averted by AKT1 and mTOR inhibitors." (PMID 36817449, 2023). "In the validation dataset, we found consistent metabolic trends in T cells; namely, we found that COVID-19 T cells downregulate key mitophagy genes FUNDC1, PINK1, and CSNK2B and upregulate key Rho GTPase genes RHOA, RHOBTB1, and ARAP3 as well as MTOR compared to HIV-1+ individuals." (PMID 36992700, 2023). "Blocking the mTOR signaling pathway may reduce the infection and replication of viruses by inducing autophagy, and inhibiting viral protein synthesis, suggesting that mTOR might be targeted to inhibit SARS-CoV-2 infection and COVID-19." (PMID 35455977, 2022). "Hence, mTOR could be an excellent therapeutic target to suppress the SARS-CoV-2 infection and COVID-19 using synthetic and natural compounds." (PMID 34179893, 2021). "Hence, mTOR might be targeted to suppress SARS-CoV-2 infection and COVID-19 using synthetic and natural compounds." (PMID 33768214, 2021). "Therefore, signaling pathways such as mTOR, UPR, and autophagy may be potential therapeutic targets for COVID-19." (PMID 34206057, 2021). "Furthermore, observations of dampened mTOR or JAK/STAT signaling in innate and adaptive immune cells could be informative for potential treatment recommendations for COVID-19, as drugs can have different influences on signaling responses in innate and adaptive immune cells." (PMID 35839768, 2022). "Moreover, from our study, the role of mTOR inhibitors in COVID-19 treatment could be hypothesized even in a non-transplant setting." (PMID 35801204, 2022). "In mono-CD16+ cells in COVID-19 patients, we found reduced lysine degradation (downregulation of NSD1, KMT2E, and SETD2) and enhanced OXPHOS, which may inhibit M2 macrophage polarization and differentiation through the cAMP and MAPK signaling pathways or the PI3K, AKT and mTOR signaling pathways." (PMID 33936072, 2021). "However, median years from transplantation to COVID-19 in our study were 5.5, which was not in the peak period of immunosupression and moreover, calcineurin inhibitors and mTOR inhibitors were mostly suspended during hospitalization due to drug interactions with lopinavir/ritonavir." (PMID 33917093, 2021). "Since mTOR is a downstream signaling molecule in the AMPK pathway, metformin combined with rapamycin may offer the possibility of restoring T-cell functionality and preventing severe progression in COVID-19, provided it is initiated early in the cytokine storm phase." (PMID 33361522, 2020).